RICTOR (RPTOR independent companion of MTOR complex 2)
Diseases named in the same sentence as RICTOR in open-access papers (continued):
Sharing a sentence is not in itself a finding about the gene and the disease.
melanoma (12 papers, 2015 to 2024). A malignant, usually aggressive tumor composed of atypical, neoplastic melanocytes. "This highlights the importance of assessing RICTOR protein levels for diagnostic and prognostic purposes, given the poor correlation between RICTOR mRNA and protein levels in melanoma patients." (PMID 38755661, 2024). "We showed that RICTOR was significantly overexpressed in melanoma and associated with bad prognoses." (PMID 34680615, 2021). "In the present study, we assessed the role of mTORC2/RICTOR in BRAF-mutated melanoma and showed that RICTOR stimulated melanoma-initiating cells (MICs) with ‘stemness’ properties." (PMID 34680615, 2021). "In the present study, we assessed the role of mTORC2/RICTOR in BRAF-mutated melanomas and their resistance to BRAF inhibition." (PMID 34680615, 2021). "Quantification of RICTOR mRNA in 22 melanoma short-term cultures confirmed that RICTOR locus amplification was associated with an increase in RICTOR mRNA level." (PMID 26356562, 2015). "RICTOR locus amplification is associated with a significant increase in RICTOR mRNA expression in melanoma." (PMID 26356562, 2015). "RICTOR amplification is therefore a frequent event in melanoma and can be associated with PTEN loss." (PMID 26356562, 2015). "To identify mTORC2-regulated molecules potentially implicated in the response of melanoma cells to targeted therapy, we have undertaken an unbiased proteomic approach to compare differentially expressed proteins between RICTOR-proficient and -deficient M14 and A375 cells under basal conditions." (PMID 38755661, 2024). "Therefore, we used these cell lines as experimental models to investigate the effects of RICTOR/mTORC2 depletion in the response of BRAF-mutated melanoma cells to BRAF/MEKi." (PMID 38755661, 2024). "Based on these notions, we have hypothesized that RICTOR/mTORC2 deficiency in BRAFV600E melanoma cells may favor BRAF/MEKi resistance." (PMID 38755661, 2024). "As the increases in STAT3 phosphorylation and AXL expression associated with a decrease in MITF expression have been associated with the resistance of melanoma cells to targeted therapies, we asked whether RICTOR/mTORC2 could play a role in resistance." (PMID 34680615, 2021). "As RICTOR overexpression led to an increase in the phosphorylation level of STAT3, it suggests that RICTOR implication in melanoma malignant behavior may be partly linked with STAT3." (PMID 34680615, 2021). "Furthermore, a recent study in melanoma indicates that RICTOR is frequently overexpressed and cooperates with NRAS mutation to stimulate melanoma proliferation." (PMID 28445935, 2017). "The CGH data showing that RICTOR is also amplified in BRAF mutated melanoma, suggest that RICTOR could also cooperate with oncogenic BRAF." (PMID 26356562, 2015). "Data mining performed on The Cancer Genome Atlas (TCGA) Melanoma PanCancer Atlas dataset showed that RICTOR expression is associated with melanoma progression and lower patient survival and might therefore be used as a novel biomarker for prognosis provided it is confirmed in independent studies." (PMID 34680615, 2021). "Our research uncovers an unforeseen role for RICTOR/mTORC2 downregulation in promoting the development of resistance to BRAFi-based therapies in BRAFV600E melanoma cells." (PMID 38755661, 2024). "As RICTOR overexpression in the TCGA dataset was correlated with the overexpression of BRAF, we focused our study on BRAF-mutated melanoma." (PMID 34680615, 2021). "To gain insights into the role of RICTOR in melanoma development, we overexpressed RICTOR in three BRAF-mutated melanoma cell lines (Colo829, A375, and SkMel5)." (PMID 34680615, 2021). "This agrees with a previous small study that identified an increased expression of RICTOR in advanced melanoma stages including liver metastases, suggesting a role of RICTOR in melanoma progression and metastasis." (PMID 34680615, 2021).
melanoma (continued). "We recently highlighted a new alteration of the PI3K pathway in melanoma, demonstrating that the RICTOR locus, which codes for the scaffolding protein of the mTORC2 complex, is frequently amplified in melanomas." (PMID 34680615, 2021). "We have shown that the RICTOR locus is frequently amplified in melanomas and that the overexpression of RICTOR in melanocytes transformed by the NRAS oncogene stimulates their clonogenicity." (PMID 34680615, 2021). "To address the role of RICTOR in melanoma, we first analyzed the expression of RICTOR in previously published gene expression datasets of patient-derived melanoma samples." (PMID 34680615, 2021). "We also showed that RICTOR contributed to melanoma resistance to BRAF inhibitors and rendered the cells very sensitive to mTORC2 inhibition." (PMID 34680615, 2021). "As observed in cultured cells, we found that RAS and RICTOR co-localized in melanoma tumors resistant to therapy." (PMID 34680615, 2021). "We showed that mTORC2/RICTOR is an important therapeutic target in BRAF-mutant melanoma, particularly in those resistant to targeted therapy where RICTOR interacts with RAS." (PMID 34680615, 2021). "To confirm the importance of mTORC2/RICTOR in the resistance of melanoma to targeted therapies in a more physiological setting, we used cells grown as spheroids." (PMID 34680615, 2021). "The pathological investigation showed that melanoma tissues overexpressing RICTOR are prone to form VM channels, and this formation was accompanied by AKT membrane translocation and an increase in MMP-2/9 secretion." (PMID 29455662, 2018). "In melanoma, where RICTOR amplification and overexpression are frequent, down-regulation of RICTOR with shRNA severely impaired the formation of vasculogenic mimicry (VM) via the AKT-MMP-2/9 pathway." (PMID 29455662, 2018). "As shown for G12VNRAS transformed Melan-a cells, human melanoma cells expressing a high level of RICTOR showed a higher level of phosphorylated AKT." (PMID 26356562, 2015). "We found that the RICTOR locus is frequently amplified and overexpressed in melanoma and that RICTOR over-expression in melanoma stimulates clonogenicity." (PMID 26356562, 2015). "Amplification of the RICTOR locus, which is frequently found in melanoma, disrupts this feedback and stimulates melanocyte and melanoma proliferation." (PMID 26356562, 2015). "Clones overexpressing RICTOR displayed an increase in AKT phosphorylation demonstrating that RICTOR overexpression can activate the PI3K/AKT pathway in melanoma." (PMID 26356562, 2015). "Using CGH array, we analyzed the amplification of the RICTOR locus in a series of 43 melanoma short-term cultures." (PMID 26356562, 2015). "To confirm these results in human melanoma cells, we used two NRAS mutated melanoma cell lines which express different levels of RICTOR." (PMID 26356562, 2015). "To shed light on the mechanisms in which RICTOR downregulation plays a role in the early adaptation of cells to BRAFi, we analyzed pathways previously implicated in BRAF/MEKi resistance in multiple melanoma cell lines." (PMID 38755661, 2024). "This uncoupling between RICTOR and phospho-AKT levels is consistent with previous evidence of alternative, mTORC2-independent mechanisms of AKT Hydrophobic motif phosphorylation, reported also to occur in BRAF-mutated melanoma cells, including A375." (PMID 38755661, 2024). "Indeed, RICTOR-depleted melanoma cells exhibit intrinsic tolerance to BRAFi, either alone or in combination with MEKi." (PMID 38755661, 2024). "Overall, our analysis revealed that RICTOR deficiency is coupled to an increased NAMPT protein expression and/or activity in BRAFV600E melanoma cells, and that both transcriptional and post-transcriptional mechanisms can account for this effect in a cell lineage-specific manner." (PMID 38755661, 2024).
melanoma (continued). "To investigate the relationships between RICTOR expression and melanoma patients’ survival, we interrogated the entire Skin Cutaneous Melanoma (SKCM) cohort of patients from the publicly available The Cancer Genome Atlas (TCGA) database with respect to overall survival (OS)." (PMID 38755661, 2024). "RICTOR deficiency alters post-translational modifications in NAMPT likely affecting its activation and/or stability, which is suggestive of a complex interplay between mTORC2 signaling and NAD+ biosynthesis in melanoma." (PMID 38755661, 2024). "We first assessed the RICTOR expression in melanocytes and BRAF-mutated melanoma by Western blot." (PMID 34680615, 2021). "To further investigate RICTOR implication in melanoma progression, we assessed whether RICTOR promoted malignant cancer phenotypes in melanoma cells in culture." (PMID 34680615, 2021). "RICTOR overexpression significantly increased melanoma cell growth as spheroids." (PMID 34680615, 2021). "Analysis of the GSE12391 melanoma data demonstrated that RICTOR was significantly overexpressed in patient-derived melanoma samples compared to nevi samples (p = 0.019), but was not significantly increased in metastatic melanoma (n = 5) compared to primary melanoma." (PMID 34680615, 2021). "Therefore, as with RICTOR, STAT3 alterations are associated with the malignant behavior phenotype in melanoma." (PMID 34680615, 2021). "RICTOR overexpression stimulated melanoma-initiating cells (MICs) with ‘stemness’ properties." (PMID 34680615, 2021). "Furthermore, in a series of 43 melanoma short-term cultures, we showed that the RICTOR locus was amplified in 19 out of 43 melanoma cell lines (44%) and that amplification was independent of the BRAF and NRAS mutation status." (PMID 34680615, 2021). "Our data suggest that the regulation of the STAT pathway by RICTOR could, at least, mediate resistance in BRAF-mutated melanoma cells." (PMID 34680615, 2021). "However, bioinformatics analysis of another set of data containing more metastatic samples (GSE7553) showed that RICTOR was significantly overexpressed in metastatic melanoma (n = 40) compared to primary melanoma (p = 0.044)." (PMID 34680615, 2021). "Moreover, the level of cyclin D1 protein was proportional to the level of RICTOR in the clones suggesting a role for RICTOR in cyclin D1 expression and melanoma proliferation." (PMID 26356562, 2015). "To investigate whether RICTOR amplification could play a role in melanoma development, we stably overexpressed RICTOR in Melan-a that had been transformed by G12VNRAS." (PMID 26356562, 2015). "As RICTOR overexpression increases melanocyte clonogenicity, we investigated whether RICTOR amplification could play a role in melanoma." (PMID 26356562, 2015). "Indeed, we found that the locus coding for RICTOR is frequently amplified in melanoma independently of BRAF or NRAS mutations and that RICTOR amplification in BRAF mutated melanoma is associated with PTEN LOH." (PMID 26356562, 2015). "However, it remains possible that other unidentified factors (like microRNAs or changes in mRNA translation) may also contribute to regulate RICTOR protein levels at different stages of melanoma progression." (PMID 38755661, 2024). "Finally, we recently demonstrated a significant reduction of cell motility and liver metastasis by RNAi-mediated suppression of RICTOR in a melanoma mouse model and a significant decrease of cancer cell motility when targeting mTORC2/RICTOR in addition to rapamycin treatment in gastric cancer cells." (PMID 35096817, 2021). "A study of the RICTOR locus by CGH array in a series of 43 melanoma short-term cultures showed that RICTOR was amplified in 19 out of 43 melanoma cell lines (44%) and that amplification was independent of the BRAF and NRAS mutation status, the most frequent mutations in melanoma." (PMID 29455662, 2018).
melanoma (continued). "We found that the RICTOR locus is frequently amplified and overexpressed in melanoma and that RICTOR over-expression in NRAS-transformed melanocytes stimulates their clonogenicity, demonstrating that RICTOR amplification can cooperate with NRAS mutation to stimulate melanoma proliferation." (PMID 26356562, 2015). "In agreement with this hypothesis, we found that RICTOR overexpression does not enhance clonogenicity of the SkMel5 melanoma cell lines, which is V600EBRAF mutated and PTEN wild type (data not shown)." (PMID 26356562, 2015). "We also observed a significant correlation between a higher expression of RICTOR and higher survival probability for LGG, SKCM, KIRC, Glioma (GSE4412-GPL97), AML (GSE12417-GPL570), Melanoma (GSE19234), and HNSC (GSE2837)." (PMID 37372460, 2023). "We highlighted a connection between mTORC2/RICTOR and STAT3 in resistant cells and revealed an interaction between RAS and RICTOR in resistant melanoma, which, when disrupted, impeded the proliferation of resistant cells." (PMID 34680615, 2021). "However, RICTOR amplification is always associated with PTEN LOH in BRAF mutated melanoma, suggesting that RICTOR overexpression may not enhance AKT activation in the presence of PTEN in these melanoma." (PMID 26356562, 2015). "Our results demonstrated that RICTOR cooperates with oncogenic NRAS by increasing AKT activation and stimulating clonogenicity of melanoma cells." (PMID 26356562, 2015). "Therefore, as a key signaling node, RICTOR contributes to BRAF-dependent melanoma development and resistance to therapy and, as such, is a valuable therapeutic target in melanoma." (PMID 34680615, 2021). "Moreover, in absence of gene amplification, RICTOR overexpression can also be associated with the deregulation of miRNA expression in tumoral cells such as miR-218 in prostate and oral cancers, the miR-424/503 cluster in colon cancers, and miR-196b in melanoma and hepotocellular carcinoma." (PMID 29455662, 2018). "Notably, the metabolic phenotype found in RICTOR-knockout keratinocytes, consisting of a switch from a glycolytic- to an OXPHOS-based energetic metabolism fueled by glutamine consumption, is reminiscent of that of targeted therapy-resistant melanoma cells." (PMID 38755661, 2024). "Thus, based on RICTOR and RAPTOR mRNA levels, these data suggest that mTORC2 and mTORC1 may play opposite roles in melanoma progression and/or therapeutic responses." (PMID 38755661, 2024). "RICTOR (Rapamycin-insensitive companion of mammalian target of rapamycin) plays a central role in PI3K pathway negative feedback in melanocytes and that its deregulation could be involved in melanoma development." (PMID 27533251, 2016). "Although we do not know yet whether RICTOR amplification is an early or late event in melanoma development, it is more likely to be a secondary event to reinforce AKT pathway activation." (PMID 26356562, 2015). "Although RICTOR overexpression was not oncogenic in Melan-a, overexpression of RICTOR in transformed G12VNRAS Melan-a stimulated their clonogenicity, demonstrating that RICTOR amplification can cooperate with NRAS mutation to stimulate melanoma proliferation." (PMID 26356562, 2015). "Activation of the PI3K/AKT pathway is frequent in melanoma and may enhance this negative feedback, so malignant cells will have to find a way to override these feedback, for example by overexpressing RICTOR." (PMID 26356562, 2015). "Therefore, if mTORC2 activity is inhibited by V600EBRAF in PTEN wild type melanoma, RICTOR overexpression will not enhance AKT activation in these cells." (PMID 26356562, 2015).
gastric cancer (8 papers, 2012 to 2022). A primary or metastatic malignant neoplasm involving the stomach. "Overexpression of RICTOR has been detected in 74.0% of gastric cancers and was associated with tumor progression, lymph node metastasis, and poor prognosis in patients with gastric cancer." (PMID 35250965, 2021). "Downregulation of RICTOR was previously shown to reduce pAKTS473 levels in gastric cancer cells, where let-7a negatively regulates translation of RICTOR mRNA." (PMID 35269443, 2022). "Also relevant to our findings, RICTOR amplification associated with sensitivity to AZD2014 in patients and cell line models of gastric cancer and SCLC." (PMID 29389967, 2018). "Tumor suppressive function of miR-218 was also reported in several types of cancer targeting several oncogenic genes, such as RICTOR (oral cancer), survivin and ROBO1 (nasopharyngeal cancer), and ROBO1 (gastric cancer)." (PMID 23159910, 2012).
prostate carcinoma (8 papers, 2017 to 2025). A carcinoma that arises from epithelial cells of the prostate gland. "Moreover, the specific knockdown of RAPTOR and RICTOR caused a decrease in cell migration, suggesting their essential role in prostate cancer cell movement." (PMID 35096817, 2021). "Interestingly, mTORC2, and more specifically RICTOR, is reported to be required for PTEN-deficient prostate tumorigenesis in mice, suggesting that targeting RICTOR/mTORC2 may be efficacious against PTEN-deficient prostate cancer in the clinic." (PMID 33105713, 2020). "For instance, the application of mTORC2 inhibitors or the silencing of RICTOR expression via RNA interference has shown promise in sensitizing prostate cancer cells to Doc in preclinical models." (PMID 40507238, 2025). "miR-218 reduces VEGF expression in prostate cancer by acting on the mTOR component RICTOR (rapamycin-insensitive companion of mammalian target of rapamycin) and by blocking the RICTOR/mTOR/HIF-1/VEGF signaling pathway." (PMID 31757094, 2019). "Collectively, our results suggest that ELAVL3 may be responsible for promoting neuroendocrine differentiation of prostate cancer cells by stabilizing RICTOR mRNA." (PMID 38016952, 2023). "Similarly, in prostate cancer, it was demonstrated that miR-218 inhibited the tumor angiogenesis of prostate cancer cells in vitro and in vivo via the regulation of RICTOR expression." (PMID 29455662, 2018). "RICTOR knockdown phenocopied miR-218 overexpression in inhibiting prostate cancer angiogenesis." (PMID 28030804, 2017). "Also, the histone dimethyl transferase WHSC1 was recently shown to transcriptionally upregulate RICTOR expression to further enhance AKT activity to promote prostate cancer metastasis, highlighting the role of the AKT/WHSC1/RICTOR cascade in prostate cancer malignancy." (PMID 29455662, 2018).
glioma (7 papers, 2017 to 2025). A benign or malignant brain and spinal cord tumor that arises from glial cells (astrocytes, oligodendrocytes, ependymal cells). "Here, we define that RICTOR localization can be used to distinguish glioma cell migrational phenotypes in an mTORC2 activity status-dependent manner." (PMID 37120454, 2023). "A higher methylation level of RICTOR predicted worse OS in glioma, liver, and endometrial cancer." (PMID 37372460, 2023). "Furthermore, RICTOR is overexpressed in adenocarcinoma, glioma, sarcoma, and many other cancer types." (PMID 32899613, 2020). "Finally, a recent study reports that glucose-dependent acetylation of RICTOR confers resistance to targeted therapy in glioma." (PMID 28445935, 2017). "Our data confirm that in gliomas, during the formation of neurospheres, the activation of UBTF commonly leads to an increase in the mRNA level of the key component of mTORC2—RICTOR." (PMID 36231068, 2022).
sarcoma (7 papers, 2016 to 2023). A usually aggressive malignant neoplasm of the soft tissue or bone. "Activation of the PI3K/AKT/mTOR pathways through different mechanisms including activation of IGFR or PI3K, loss of PTEN, RICTOR amplification and/or increased p-AKT has been reported in LMS and other sarcoma subtypes." (PMID 26952093, 2016). "Genes located in 5p that have been suggested as possible amplicon targets in sarcomas include NKD2, TERT, IRX2, TRIO, AMACR, SKP2 and RICTOR." (PMID 28652867, 2017).